CXCL3 (C-X-C motif chemokine ligand 3)
Diseases named in the same sentence as CXCL3 in open-access papers (continued):
Sharing a sentence is not in itself a finding about the gene and the disease.
lymph node metastasis (4 papers, 2020 to 2025). "Comparative analysis of the CXC chemokine/receptor genes revealed significantly higher expression levels of genes encoding ELR+ CXC chemokines/receptors (CXCL1, CXCL3, CXCL6, CXCR1, and CXCR2) in bone metastases relative to lymph node metastases." (PMID 33195424, 2020). "Plasma CXCL3 was also related to tumor size (P = 0.034), staging (P < 0.001), tumor stage (P = 0.003), differentiation (P = 0.001), and lymph node metastasis (P = 0.007), but not to sex (P = 0.853), age (P = 0.691), tumor site (P = 1.347), or distant metastasis (P = 1.218)." (PMID 35664357, 2022). "Further, the level of CXCL3 in plasma of CRC patients was positively related to CEA (r = 0.50), with the plasma expression of CXCL3 in CRC related to tumor size, staging, tumor stage, differentiation, and lymph node metastasis, but not to sex, age, tumor site, or distant metastasis." (PMID 35664357, 2022).
ovarian carcinoma (4 papers, 2021 to 2025). A malignant neoplasm originating from the surface ovarian epithelium. "The transcriptional levels of CXCL1, CXCL8, CXCL10, CXCL11, CXCL12, CXCL13, and CXCL14 were significantly elevated while CXCL3 was obviously reduced in ovarian cancer vs normal ovarian tissue." (PMID 33763130, 2021). "Although CXCL2 and CXCL3 belong to the CXC chemokine family, their roles in the polarization of macrophages in ovarian cancer remain undefined." (PMID 41360767, 2025).
rheumatoid arthritis (4 papers, 2020 to 2024). A chronic, systemic autoimmune disorder characterized by inflammation in the synovial membranes and articular surfaces. "The Enrichr pathway assignment analysis (KEGG 2021 Human database) additionally revealed enrichment of chemokine encoding genes (CXCL1, CXCL2, CXCL3, CXCL6, CXCL5, CXCL8, CCL2) which were aligned to several pathways like amoebiasis and rheumatoid arthritis." (PMID 35646693, 2022).
breast tumor (3 papers, 2017 to 2024). "Similar to what we observed in the current study, a recent research demonstrated that CXCL3 was overexpressed in most cases of aggressive prostate and breast tumors, and its expression was associated with poor prognosis." (PMID 29209625, 2017). "However, IL1R1, ILRAP, IL6ST, CXCL3, CXCL5, and CXCL6 gene expression was higher in normal adjacent tissue than in breast tumor tissue." (PMID 39201290, 2024). "However, IL1R1, ILRAP, IL6ST, CXCL3, CXCL5, and CXCL6 gene expression levels were higher in normal adjacent tissue than in breast tumor tissue indicating that the surrounding non-tumor tissue could also present an inflammation." (PMID 39201290, 2024).
Cirrhosis (3 papers, 2020 to 2025). A chronic disorder of the liver in which liver tissue becomes scarred and is partially replaced by regenerative nodules and fibrotic tissue resulting in loss of liver function. "High gene expression levels of CXCL3, CXCL8, and IL1A also correlate with HCV-associated liver inflammation, cirrhosis, and HCC." (PMID 34497613, 2021).
leukemia (3 papers, 2013 to 2024). A malignant (clonal) hematologic disorder, involving hematopoietic stem cells and characterized by the presence of primitive or atypical myeloid or lymphoid cells in the bone marrow and the blood. "Furthermore, HSC-prog cells showed more interactions with other cells through known ligand–receptor pairs, such as leukaemia-associated ligands CXCL2, CXCL3, and FLT3, signalling to the receptors CXCR1 and CXCR2 expressed by CD14-mono and NK cells." (PMID 37615858, 2024).
medulloblastoma (3 papers, 2012 to 2016). A malignant, invasive embryonal neoplasm arising from the cerebellum. "That is, via stimulation of CXCL3 gene transcription, thyroid hormone might increase outmigration of cerebellar granule neuron precursor cells from the external granular layer of the cerebellum and reduce the risk of medulloblastoma in pediatric patients." (PMID 27493972, 2016). "It is possible that the biology of another CNS tumor, medulloblastoma, may be affected by thyroid hormone and hormone analogues, but in a wholly different manner and working via a chemokine, CXCL3." (PMID 27493972, 2016). "If, as we propose, T4 via its receptor on αvβ3 enhances CXCL3 gene expression, then the presence of the hormone in the course of brain development would support the normal outmigration of GCPs from the EGL and contribute to minimization of risk of medulloblastoma." (PMID 27493972, 2016).
Salmonella Infections (3 papers, 2011 to 2025). Infections with bacteria of the genus SALMONELLA. "Confirming the initiation of an epithelial immune response by the intestinal barrier model, Salmonella infection induced the expression of both coding (SOCS3, CXCL2, CXCL3) and noncoding (NEAT1) immune-associated RNAs in IECs." (PMID 32071273, 2020).
Stroke (3 papers, 2016 to 2022). Sudden impairment of blood flow to a part of the brain due to occlusion or rupture of an artery to the brain. "In our study, 415 mRNAs were found to be associated with the effect of 20(R)-Rg3 on stroke recovery, while the expression of these genes, such as Tagln, Vim, Ptges, Pax1, Cxcl3 and Ccl20, was also significantly altered in our sequencing results." (PMID 35268674, 2022). "Similarly, at 7 days after stroke, CXCL3 protein levels were lower in the inhibitor group, as compared to controls; this decrease was consistent throughout all samples and statistically significant." (PMID 27829437, 2016).
adenoma (2 papers, 2011 to 2023). A neoplasm arising from the epithelium. "And the 6 coincident genes significantly enriched in adenoma and carcinoma were DEFA6, SOX9, ID1, L1TD1, CXCL3, and ODC1." (PMID 36944972, 2023). "In C2 goblet cells, during the process from normal colon to adenoma and from adenoma to carcinoma, several continuously highly expressed genes were found, including DEFA6, SOX9, ID1, L1TD1, CXCL3, and ODC1." (PMID 36944972, 2023). "CXCL1, CXCL2, CXCL3, CCL20, and IL-8 had increased expression in the adenoma and adenocarcinoma compared to normal colonic mucosa." (PMID 21249124, 2011).
colorectal adenoma (2 papers, 2020 to 2021). An adenoma that arises from the colon or rectum. "CXCL3 has been found to be highly expressed in colorectal adenomas." (PMID 34070979, 2021).
esophageal cancer (2 papers, 2023). A primary or metastatic malignant neoplasm involving the esophagus. "Similar correlations were observed in esophageal carcinoma, with CXCL1, CXCL2, CXCL3, and PPBP negatively correlated with EMT, CXCL5 and CXCL6 positively correlated with EMT, and CXCL8 not correlated with EMT." (PMID 37686093, 2023).
esophageal squamous cell carcinoma (2 papers, 2020 to 2022). Esophageal squamous cell carcinoma (ESCC) is a type of esophageal carcinoma (EC) that can affect any part of the esophagus, but is usually located in the upper or middle third. "CXCL3 is a known angiogenic chemokine and participates in the chemotaxis of neutrophils, in addition, CXCL3 inhibits the growth of esophageal squamous cell carcinoma by attracting neutrophils." (PMID 36118865, 2022).
gastric adenocarcinoma (2 papers, 2023 to 2024). "To decipher the cellular state and function of macrophages in the process of intestinal-type gastric adenocarcinoma carcinogenesis, we reclustered all of the macrophages into five clusters, including macrophage_IL1B, macrophage_CHI3L1, macrophage_CXCL3, macrophage_IFIT3 and macrophage_FOLR2." (PMID 39702278, 2024). "This correlation has been observed in stomach adenocarcinoma with respect to CXCL1, CXCL3, CXCL6, and CXCL8." (PMID 37686093, 2023).
Hepatitis (2 papers, 2017 to 2021). Inflammation of the liver. "The liver transcriptional expressions of CXCL1, CXCL2, CXCL3, CXCL5, CCL2, and CCL6 significantly increased in WT and IL-33 KO mice during L2-MHV3-induced hepatitis compared to those in control PBS-injected mice as soon as 48 h PI and at 72 h PI." (PMID 28607531, 2017).
Hypertension (2 papers, 2017 to 2022). The presence of chronic increased pressure in the systemic arterial system. "Moreover, TREM-1 (that mediates inflammatory cardiac injury), CINC2 (CXCL-3) that is induced by IL-1 (and also called macrophage inflammatory protein 2 beta, MIP-2β), and fibroblast growth factor binding protein (FGF-BP) (that is implicated in hypertension) were also suppressed in ZO-C heart." (PMID 28408970, 2017). "Meanwhile, we found that C5AR1, CCL4L2, CCL4, CCL20, CD163, CXCL3, and CXCL12 were only expressed in disease a, suggesting the recruitment of inflammatory factors and promotion of the inflammatory response were both more obvious in hypertension-induced AD." (PMID 35800890, 2022).
inflammatory bowel disease (2 papers, 2015 to 2017). A spectrum of small and large bowel inflammatory diseases of unknown etiology. "The inflammation and inflammatory bowel disease (IBD) disorders had many commonly modulated genes that were also found in the String analysis that were common with the disorders which included IL-8, ICAM1, RELB, NFκBIA, TNFAIP3, LIF, CXCL1, CXCL2, CXCL3, CXCL10, and TNF-α." (PMID 28099447, 2017).
keloid (2 papers, 2021 to 2025). An irregularly shaped, elevated mark on the skin caused by deposits of excessive amounts of collagen during wound healing. "At the same time, it can be seen that CXCL3, another member of the CXC chemokine subfamily, usually acts as a neutrophil chemotactic agent in inflammation and is overexpressed in keloid fibroblasts." (PMID 35082796, 2021).
neuropathy (2 papers, 2019 to 2022). A disorder affecting the nervous system that manifests with pain, tingling, numbness, and/or muscle weakness. "Specifically, these DEGs were associated with neuropathy-related pathways, such as GABRD, GABRP, TBX1, and SOX10, and inflammatory responses such as CXCL3, CXCL12, TNF, and IL6." (PMID 36147849, 2022). "CXCL3 is strongly expressed in a number of tumorous conditions; however, its role in the context of neuropathy has yet to be studied." (PMID 31616413, 2019).
Obesity (2 papers, 2020 to 2023). Accumulation of substantial excess body fat. "Strikingly, ob-dT bASCs already displayed an enhanced gene expression of CXCL2, CXCL1, CXCL3, FGF2 and CCL2, compared to ln-dT bASCs, suggesting a crucial impact of obesity on bASCs." (PMID 36710348, 2023).
oral squamous cell carcinoma (2 papers, 2022 to 2023). "In addition, CXCL3 affected the migration and invasion of airway smooth muscle cells, uterine cervical cancer cells and oral squamous cell carcinoma cells via mitogen-activated protein kinase (MAPK), with particular involvement of the extracellular signal-regulated kinase (ERK) pathway (ERK/MAPK)." (PMID 36401313, 2022). "In addition, CXCL3 promotes cell growth and movement via autocrine/paracrine mechanisms involving Jak-STAT and MAPK signaling pathways in prostate and oral squamous cell carcinoma." (PMID 37893029, 2023).
rectal adenocarcinoma (2 papers, 2021 to 2023). "Data from TCGA and GEO verified that overexpression of gene CXCL1 and CXCL3 portends unfavorable survival outcomes in patients with rectal adenocarcinoma." (PMID 34269159, 2021). "In conclusion, the CXCL1 and CXCL3 genes may have potential for prognosis and molecular targeted therapy of rectal adenocarcinoma." (PMID 34269159, 2021). "In rectum adenocarcinoma, CXCL1 and CXCL3 negatively correlated with EMT, while CXCL5, CXCL6, PPBP, and CXCL8 were positively correlated." (PMID 37686093, 2023). "In rectal adenocarcinoma, four hub genes including CXCL1, CXCL2, CXCL3, and GNG4 were highly expressed at the gene and RNA levels." (PMID 34269159, 2021).
skin inflammation (2 papers, 2018 to 2024). "Previous research has indicated that alpha-toxin phenol-soluble modulins (PSMs) secreted by Staphylococcus aureus can significantly induce the expression of pro-inflammatory chemokines such as Cxcl1 and Cxcl3 in human primary keratinocytes, exacerbating skin inflammation." (PMID 39684557, 2024).
thyroid cancer (2 papers, 2023 to 2024). "According to transcriptome sequencing, antitumor chemokine regulatory genes (CXCR3) were upregulated, and protumor chemokine regulatory genes (CCR3, CXCL1, CXCL2, CXCL3, CXCL8, and CXCR2) were downregulated after MWA in thyroid cancer." (PMID 38779358, 2024).
ZIKV infection (2 papers, 2022). "Adult patients in the acute phase of ZIKV infection produce high levels of chemokines such as CXCL3, CXCL9, CXCL10 and IL15 in the serum, as well as microcephaly babies in the cerebrospinal fluid, especially when developing neurological symptoms." (PMID 36142200, 2022). "CXCL3, CXCL8, and PTGS2 were all slightly, but not significantly, induced following ZIKV infection, and the expression of all three inflammatory mediators was significantly decreased in the EGR1−/− infected cells as compared to the WT mock-infected cells." (PMID 35746681, 2022).
arbovirus infection (1 paper, 2025). A viral infection that is transmitted by an arthropod. "This included a crucial set of genes that have been implicated in increased susceptibility to arbovirus infection, including neutrophil-attracting chemokines (CXCL1, CXCL3, CXCL8)." (PMID 41150413, 2025).
Bovine mastitis (1 paper, 2024). INFLAMMATION of the UDDER in cows. "In a recent study, our group validated the inhibitory effect of glyceryl 1,3 distearate in suppressing the IL1β, IL6, IL8, and CXCL3 overexpression induced by LPS from Escherichia coli, a bacterium causing bovine mastitis." (PMID 39193343, 2024).
brain tumor (1 paper, 2025). "CAG inhibited the activity of the JAK/STAT signaling pathway in LLC brain tumor tissues, thereby downregulating the expression of neutrophil chemotaxis-associated cytokines, including CXCL3 and CCL5." (PMID 40687724, 2025).
cervical squamous cell carcinoma (1 paper, 2023). A squamous cell carcinoma arising from the cervical epithelium. "In another example, cervical squamous cell carcinoma and endocervical adenocarcinoma exhibited a negative correlation between the expression of CXCL1, CXCL6, and CXCL8 and EMT, whereas the expression of CXCL3, CXCL5, and PPBP positively correlated with EMT." (PMID 37686093, 2023).
dementia (1 paper, 2025). Loss of intellectual abilities interfering with an individual's social and occupational functions. "Through senescent microglia profiling, a microglia-derived senescence associated secretory factor, CXCL3, that drives AD dementia-relevant behavioral alterations in mouse models was identified." (PMID 40542975, 2025).
diabetes (1 paper, 2023). "The downregulated genes in cluster 9 in the diabetes group on day 1 including Arg1, Cxcl3, Plac8, Saa3 were enriched in response to external biotic stimulus, response to other organism, response to biotic stimulus, defence response (Supplementary 11)." (PMID 36445632, 2023).
diabetic retinopathy (1 paper, 2018). "While virtually nothing is known regarding CXCL2 and CXCL3 in diabetic retinopathy, CXCL8 (also called IL-8) has consistently been found to be elevated in the vitreous of diabetic retinopathy patients." (PMID 29626212, 2018).
E. coli infection (1 paper, 2023). "Based on DEGs, WGCNA, and MCODE, key genes associated with E. coli infection were discovered, including CXCL3, HSPA1B, TNF, and PLPP3." (PMID 38066783, 2023).
enteroviral infection (1 paper, 2013). "Analysis of the cytokine/chemokine-profile following enteroviral infection with a cytometric bead array and Q-PCR revealed an enhanced secretion of PanGRO (CXCL1, CXCL2 and CXCL3), IL8 and CCL5." (PMID 23305147, 2013).
epilepsy (1 paper, 2021). A brain disorder characterized by episodes of abnormally increased neuronal discharge resulting in transient episodes of sensory or motor neurological dysfunction, or psychic dysfunction. "Secondly, various inflammatory mediators such as CXCL9, CXCL3, and IL-6 have been shown to be dysregulated in patients with drug-resistant epilepsy." (PMID 34497517, 2021).
head and neck squamous cell carcinoma (1 paper, 2021). A squamous cell carcinoma that arises from any of the following anatomic sites: lip and oral cavity, nasal cavity, paranasal sinuses, pharynx, larynx, and salivary glands. "However, the mechanisms of CXCL3 in head and neck squamous cell carcinoma (HNSCC) remain unclear." (PMID 34870709, 2021).
helminth infection (1 paper, 2015). "As CXCL2 and CXCL3 have been reported to promote repair processes, including smooth muscle cell migration, we investigated the expression of these chemokines during helminth infection in vivo." (PMID 25806513, 2015).
hepatitis B virus infection (1 paper, 2016). A viral infection caused by the hepatitis B virus. "Investigation of the correlation between CXCL3 and clinicopathological features showed that a high level of CXCL3 was significantly associated with vascular invasion and TNM stage, and was negatively correlated with Hepatitis B virus infection." (PMID 27255419, 2016).
hypertensive retinopathy (1 paper, 2022). Retinopathy due to hypertension. "We evaluated the expression levels of a series of chemokines (CXCL1, CXCL2, CXCL3 and CXCL5) and their receptor CXCR2 in Ang II-treated retinas to investigate the role of chemokines and their receptors in hypertensive retinopathy." (PMID 35981418, 2022).
injury (1 paper, 2020). Damage inflicted on the body as the direct or indirect result of an external force, with or without disruption of structural continuity. "Genes that encode inflammatory cytokines (such as TNF and IL1), chemokines (such as CCL2, CXCL1, CXCL2, and CXCL3) and cell proliferation-related proteins (such as CycD and CycE) were downregulated when Cyp2c29 was overexpressed in a mouse model of liver injury." (PMID 32587777, 2020).
leptospirosis (1 paper, 2024). A contagious bacterial infection caused by spirochetes of the genus Leptospira. "It has been described that CXCL5 leads to CXCL3, CXCL1, and CXCL14 expression, which are all potent chemoattractants for neutrophils, indicating the occurrence of this mechanism on leptospirosis immune response." (PMID 39534703, 2024).
leukocytosis (1 paper, 2013). "On the other hand, the correlation between CXCL3 concentration and milk leukocytosis was rather high at the beginning of ASR, and it can be speculated that the initial high CXCL3 milk concentration has contributed to the transepithelial migration of neutrophils." (PMID 23696826, 2013).
lung fibrosis (1 paper, 2014). "Lack of CXCR2, the receptor for CXCL3/KC, one of the main neutrophil chemotactic agents in mice, resulted in decreased lung fibrosis along with decreased accumulation of neutrophils in the airways." (PMID 24970330, 2014).
malignant hypertension (1 paper, 2021). Severe hypertension that is characterized by rapid onset of extremely high blood pressure and hypertension-mediated organ damage. "CC-chemokine ligand 5 (CCL5) and C-X-C motif chemokine ligand 3 (CXCL3) showed no induction under malignant hypertension." (PMID 34528115, 2021).
meningitis (1 paper, 2023). A disorder characterized by acute inflammation of the meninges of the brain and/or spinal cord. "Compared to BMECs, astrocytes release significantly higher levels of CXCL3 in response to stimulation with the meningitis E. coli infection, suggesting that astrocytes are the main source of CXCL3, which acts on other cells and causes a series of biological effects." (PMID 37445610, 2023).
mucinous adenocarcinoma (1 paper, 2020). An invasive adenocarcinoma composed of malignant glandular cells which contain intracytoplasmic mucin. "In our research, we find that the CXCL3 is associated with tumor histology types and is in high expression in adenocarcinoma, especially in Mucinous adenocarcinoma." (PMID 33552958, 2020).
non-small cell lung carcinoma (1 paper, 2022). A group of at least three distinct histological types of lung cancer, including non-small cell squamous cell carcinoma, adenocarcinoma, and large cell carcinoma. "In non-small-cell lung cancer (NSCLC), circMET promotes proliferation, metastasis, and immune evasion by regulating Mir-145-5p/CXCL3." (PMID 35802745, 2022).